LAG3 (lymphocyte activating 3)
Diseases named in the same sentence as LAG3 in open-access papers (continued):
Sharing a sentence is not in itself a finding about the gene and the disease.
melanoma (continued). "LAG3-MHC-II interaction contributes to melanoma resistance to apoptosis." (PMID 37304291, 2023). "Taken together, these results are consistent with LAG-3 playing a key role in PD-1 and/or CTLA-4 blockade resistance, and provides additional rationale for targeting LAG-3 (in combination with PD-1) as a strategy to overcome ICI resistance in melanoma and possibly other solid tumor types." (PMID 37795090, 2023). "Furthermore, numerous clinical trials are underway to investigate new anti-LAG-3 molecules in advanced solid tumors including melanoma." (PMID 37004702, 2023). "Engagement of HLA class-II molecules on melanoma cells by its ligand LAG-3 expressed on melanoma-infiltrating T cells might trigger an immune escape pathway." (PMID 38201531, 2023). "The same study also found LAG-3+ pDCs in melanoma-invaded lymph nodes that were IL-6 positive." (PMID 36960057, 2023). "While studies evaluating LAG-3 therapies rarely profile NK cells, one study evaluating the response of patients with melanoma to a combination of anti-LAG-3 and anti-PD-1 found that adaptive LAG-3+ NK cells were most prominent in those who responded to immunotherapy." (PMID 38090565, 2023). "Specifically, the discovery of antibodies directed to immune checkpoint molecules such as programmed cell death protein 1 (PD-1) and cytotoxic T-lymphocyte-associated-protein 4 (CTLA-4), and, more recently, lymphocyte activation gene 3 (LAG-3), have drastically prolonged survival in melanoma." (PMID 37900283, 2023). "In accordance with this hypothesis, advanced melanoma patients with ≥1% tissue LAG-3 expression detected by IHC were shown to have longer median PFS after ICB treatment." (PMID 37342338, 2023). "In vitro experiments have demonstrated that MHC class II-expressing melanoma cells can stimulate LAG3+ pDCs to mature and produce IL-6, a finding confirmed in vivo where LAG3+ pDCs displayed elevated IL-6 production and an activated phenotype in close proximity to melanoma cells." (PMID 37569880, 2023). "In addition, recent clinical trials of LAG-3/PD-1 combination therapy for melanoma had positive outcome." (PMID 37007114, 2023). "Paired sc-RNA and sc-TCR-seq analysis of melanoma patient specimens demonstrated that clonal T cells in periphery are in a more activated cellular state (CCL5+GZMB+KLRG1+KLRK1+CX3CR1+) than their counterparts in TME (PD-1+LAG3+CTLA-4+TIM-3+TIGIT+)." (PMID 37881432, 2023). "The striking synergy between LAG-3 and PD-1 has been demonstrated in murine melanoma, colon cancer, and ovarian tumor models, where the dual blockade against LAG-3 and PD-1 effectively controlled tumor progression that was resistant to respective monotherapies." (PMID 37928556, 2023). "In the melanoma setting, the most evaluated checkpoints are PD-L1 and LAG-3." (PMID 38201531, 2023). "RELATIVITY-047, a global, randomized, double-blind Phase 2/3 study of patients with metastatic or unresectable melanoma in the first-line setting, recently demonstrated the clinical success of an anti-LAG3/PD-1 combination therapy and led to the FDA approving relatlimab with nivolumab." (PMID 38041068, 2023). "Additionally, in particular settings such as cutaneous T-cell lymphoma and melanoma, the LAG-3 expression is negatively regulated by microRNA-146 and histone deacetylase 6 inhibition." (PMID 37509517, 2023). "A recent study on melanoma found CCL4-expressing CD8+ T cells were robust expressors of Lag-3, which supports the notion that this subset might be exhausted." (PMID 35720272, 2022). "Recent clinical trial data also support dual blockade of LAG3 and PD-1 in melanoma." (PMID 35626103, 2022). "An in vitro study conducted on melanoma cells demonstrated that the interaction between LAG-3 and LSECtin may inhibit IFNγ production by antigen-specific effector T cells." (PMID 36077354, 2022).
melanoma (continued). "Although LAG3 inhibitors are still in phase I/II clinical trials regarding the immunotherapy of gastric cancer and the efficacy is uncertain, clinical trial results of melanoma provide some about the potential effect of anti-LAG3 inhibitors in gastric cancer immunotherapy." (PMID 36042469, 2022). "Antibody BMS-986207 is being tested in phase I and II clinical trials, for the treatment of solid tumors as monotherapy (NCT02913313) or in combination with nivolumab (NCT04570839, NCT05005273), in melanomas alone or in combination with anti-LAG3 (NCT04150965)." (PMID 36140182, 2022). "The function of LAG3 in melanoma needs further experiments to verify." (PMID 35530341, 2022). "Similarly, antigen-specific T cells (Melan-A/MART-1) extracted from metastases of melanoma patients exhibit increased levels of LAG-3 and other IRs (CTLA4, TIM3) compared with the expression on peripheral blood lymphocytes." (PMID 36077354, 2022). "As revealed in another study, HDAC6 inhibition could suppress the T cell expression levels of PD-1, TIM-3 and LAG-3, relieving T cell suppression in melanoma patients." (PMID 35585975, 2022). "Importantly TRM express an array of immune checkpoints such as PD-1, CTLA-4 and LAG-3, which are all current targets of ICIs in melanoma." (PMID 36466880, 2022). "In melanoma, PD-1 is co-expressed with LAG-3 on CD103+ CD8+ TRM cells." (PMID 36077846, 2022). "In contrast, melanoma patients with LAG3 expression in less than 1% of their immune cells had an average ORR of 5% (n = 22), indicating that LAG3 inhibition therapy may be a specific, targeted therapy for patients with high expression of LAG3 in their TME." (PMID 35345849, 2022). "Interestingly, this interaction also affected antitumor immunity in MHC-II-expressing melanoma cells, whereby these were protected from apoptosis promoted by LAG3-overexpressing T cells." (PMID 36009442, 2022). "However, in some tumors, such as gastric cancer and melanoma, higher LAG3 expression indicates a better prognosis." (PMID 35111155, 2021). "Furthermore, LAG3+ pDCs are involved in the melanoma environment and interact with HLA-DR-expressing tumor cells in vivo." (PMID 34267742, 2021). "LAG-3+ pDCs possess tight contacts with melanoma cells and form IL-6 actively." (PMID 32902664, 2021). "IMP321 and relatlimab are promising monoclonal antibodies targeting LAG3 in melanoma." (PMID 35111155, 2021). "BMS-986016 (Relatlimab), the first IgG4 monoclonal antibody developed to target LAG-3, has been clinically tested in a variety of cancers and has been shown to be effective in combination with Nivolumab in advanced melanoma patients treated with anti-PD-1/anti-PD-L1 therapy." (PMID 34869005, 2021). "However, in some tumors, such as gastric cancer and melanoma, a higher expression of LAG3 indicates a better prognosis." (PMID 35111155, 2021). "However, since NK cells do not generally interact with MHC-II, alternative ligands have been proposed for LAG-3 such as liver sinusoidal endothelial cell lectin expressed on melanoma cells, and galectin-3, expressed on stromal cells commonly found in the TME." (PMID 33946954, 2021). "Consequently, tumor-infiltrating pDCs expressing LAG-3 have been shown to contribute to an anti-inflammatory environment in melanoma patients." (PMID 33374804, 2020). "Beyond, the demonstrated correlations of LAG3 DNA methylation with known clinicopathological and molecular features of immune response provide first evidence of LAG3 methylation as a potential prognostic and predictive biomarker in melanoma patients." (PMID 32861198, 2020). "Additionally, we present first evidence for LAG3 DNA methylation as a predictive biomarker for response to immune checkpoint inhibitors in melanoma." (PMID 32861198, 2020). "However, little is known about the biological and clinical significance of LAG3 DNA methylation in melanoma and its microenvironment." (PMID 32861198, 2020).
melanoma (continued). "Our results provide valuable insights in the prognostic significance of LAG3 in melanoma." (PMID 32861198, 2020). "Melanoma cell lines, however, showed hypermethylation in the LAG3 promoter region." (PMID 32861198, 2020). "Importantly, although LAG-3 blockade alone had a limited effect on suppressing melanoma cell growth, and SB415286 showed some inhibitor effects, their combination significantly enhanced CD8+ T cell cytolytic responses against lymphoma target cells in vitro." (PMID 32526891, 2020). "Beyond, LAG3 methylation needs to be considered a valuable prognostic biomarker and in future could even have therapeutic applications in melanoma." (PMID 32861198, 2020). "On the opposite, high expression of MHC class II as a ligand for LAG3 on tumor cells seems to portend a poorer prognosis and may indicate exhaustion of tumor infiltrating T cells in melanoma." (PMID 32861198, 2020). "However, we confirmed a tumor cell-intrinsic and inducible mRNA expression of LAG3 and a regulative role of LAG3 DNA methylation in the melanoma cell line A375." (PMID 32861198, 2020). "The primary focus of our study was on the epigenetic regulation of LAG3 in melanoma." (PMID 32861198, 2020). "IC inhibitors targeting programmed cell death receptor 1 (PD-1) and its ligand (PD-L1), cytotoxic T lymphocyte-associated protein 4 (CTLA-4), and lymphocyte activation gene-3 (LAG-3) are over-expressed in several cancers, such as lung cancer, melanoma, and triple-negative breast cancer (TNBC)." (PMID 30506221, 2019). "The interaction between highly constitutive expression of MHC class II molecules at the surface of melanoma cells and LAG-3 greatly expressed on melanoma-specific CD4+ T cells elicits a local TNF-rich inflammatory environment, reducing the cytotoxic CD8+ T cell responses." (PMID 32039024, 2019). "One such inhibitory receptor that is expressed on CTLs and Treg cells during exhaustion is lymphocyte activation gene 3 protein (LAG3), with efficacy studies demonstrating an enhanced response in melanoma patients treated with both nivolumab and relatlimab, an anti-LAG3 mAb." (PMID 31788395, 2019). "Indeed, preliminary trial results show LAG3+PD1 combination blockade has a similar safety profile to PD1 monotherapy in advanced melanoma patients." (PMID 30653605, 2019). "The striking synergy between LAG-3 and PD-1 has been reported in murine melanoma, fibrosarcoma, and colorectal adenocarcinoma models, the combinatorial blockade against LAG-3 and PD-1 effectively eradicate most established tumors, which are largely resistant to single agent treatment." (PMID 30603054, 2018). "Additionally, multiple clinical trials have demonstrated the validity of LAG-3 as a vaccine adjuvant for melanoma and prostate cancer as well as of LAG-3 in combination with chemotherapy for the treatment of metastatic breast cancer." (PMID 29725606, 2018). "In agreement, LAG-3 mediates resistance to apoptosis on MHC-II expressing melanoma cells." (PMID 28970830, 2017). "Furthermore, emerging research has identified other biomarkers, including TIGIT, VISTA, and LAG-3, as potential targets in future immunotherapies, and some studies have already begun testing these drugs in treating cancers such as melanoma, yielding promising results." (PMID 40075698, 2025). "The treatment landscape for advanced melanoma has transformed significantly with the advent of BRAF and MEK inhibitors (BRAF/MEKi) targeting BRAFV600 mutations, as well as immune checkpoint inhibitors (ICI) like anti-PD-1 monotherapy or its combinations with anti-CTLA-4 or anti-LAG-3." (PMID 39859576, 2025). "Evaluation of melanoma data from The Cancer Genome Atlas (TCGA) revealed strong positive correlations between PDPN expression and several immune checkpoint receptors, including PD-L1, CTLA4, LAG3, TIGIT, and BTLA, with the association with PD-L1 (CD274) being the most prominent (r=0.504, p<0.001)." (PMID 41573582, 2025).
melanoma (continued). "Given these limitations, a randomized phase III trial in melanoma showed that combined inhibition of PD-1 and LAG-3 resulted in improved clinical outcomes, suggesting that targeting PD-1 and LAG-3, rather than PD-1 and CTLA-4, could be a safer and potentially more effective strategy in OCCC." (PMID 41383608, 2025). "Interestingly, increased expression of the inhibitory heterodimer receptors NKG2A+ and CD94+ on CD8+ T cells, both in murine cancer models and in patients with advanced melanoma, resulted from blocking both LAG-3 and PD1, possibly as a compensatory mechanism to prevent immunopathology." (PMID 40299510, 2025). "The combination of favezelimab (anti-Lag3) and pembrolizumab (anti-PD-1) is in PhIII studies for colorectal cancer and non-Hodgkin’s lymphoma; the combination of fianlimab (anti-Lag3) and cemiplimab (anti-PD-1) is in PhIII studies for non-small cell lung cancer and melanoma." (PMID 39234253, 2024). "Future experiments combining MCL1 inhibitors with multiple ICIs (anti-PD-1 + anti-CTLA4 or anti-PD-1 + anti-LAG3) may help identify optimal treatment strategies for melanoma, as well as many other tumors where MDSCs prevent the efficacy of conventional therapies." (PMID 38459020, 2024). "Notably, the combination of anti-LAG3 and anti-PD-1 may be more advantageous, as it has shown a better safety profile in advanced melanoma compared to the combination of anti-CTLA-4 and anti-PD-1." (PMID 39404378, 2024). "Besides MHC-II, other ligands of LAG-3 include galectin-3 found on tumor and tumor stromal cells, liver sinusoidal endothelial cell lectin (LSECtin) which is expressed on liver and melanoma cells, and fibrogen-like protein 1 (FGL1) secreted from hepatocytes and tumor cells." (PMID 37304291, 2023). "With respect to the future, new combinations with novel agents, such as the anti-lymphocyte activation gene-3 (LAG-3) mAb relatlimab, and potentially also the neo-adjuvant treatment of patients with nodal macro-metastases will be of importance in shaping the field of adjuvant melanoma treatment." (PMID 35158952, 2022). "Thus, the inhibition of two immune checkpoints, LAG-3 and PD-1, provided a greater benefit with regard to progression-free survival than inhibition of PD-1 alone in patients with previously untreated metastatic or unresectable melanoma." (PMID 35902427, 2022). "Indeed, various melanoma infiltrating cells exhibit LAG-3 expression." (PMID 34572799, 2021). "In a recent study, melanoma patients showed higher proportions of both circulating and tumor-infiltrating γδ T cells expressing LAG-3 compared to control groups, suggesting that LAG-3 may be crucial for immune escape and tumor progression by inhibition of γδ T cells." (PMID 34572874, 2021). "Therefore, LAG3+ pDCs may indirectly drive myeloid-derived suppressor cell (MDSCs)-mediated immunosuppression through the engagement of MHC class II+ melanoma cells." (PMID 34267742, 2021). "Preliminary data from a clinical trial of LAG-3 antibody (liratrimab) in combination with nivolumab in melanoma patients suggested that it was more effective than nivolumab alone, suggesting that the anti-LAG-3 antibody may have clinical efficacy as a third ICI pathway following PD-1 and CTLA-4." (PMID 34685400, 2021). "Furthermore, the role of LAG3 methylation in melanoma cells needs further evaluation." (PMID 32861198, 2020). "To test the hypothesis that LAG3 expression is controlled by DNA methylation, we correlated the methylation levels of 16 CpG sites within the LAG3 gene with RNA-Seq expression data of N = 468 melanoma samples from the TCGA." (PMID 32861198, 2020). "In addition, we demonstrated that LAG3 mRNA is expressed at low levels in a melanoma cell line and could be induced by demethylating agents, thus confirming a transcriptional regulation of LAG3 via DNA methylation." (PMID 32861198, 2020).
melanoma (continued). "This was accompanied by the expression of proliferation marker Mki67 and exhaustion markers Pdcd1, Lag3, and Tim3 at the RNA level, which is consistent with reports of cell differentiation from naive cells, through a transitional state, toward dysfunction in human melanoma." (PMID 32433953, 2020). "The association of LAG-3-and PD-1-inhibitors may be able to overcome resistance and enhance responses, as suggested by preliminary results of the CA224-020 clinical trial (NCT01968109) including melanoma patients progressed on prior anti-PD-1/PD-L1 therapy." (PMID 32516941, 2020). "However, knowledge of tumor cell-intrinsic expression of the LAG3 protein in melanoma is scarce." (PMID 32861198, 2020). "Additionally, melanoma resistance to FAS-mediated apoptosis has been proposed as a mechanism of immune escape mediated by tumor cells expressing MHC class II through engagement with LAG-3 (CD223) expressed on TILs." (PMID 30941125, 2019). "However, LAG-3 is involved in alternative activation of plasmacytoid DCs in melanoma lesions." (PMID 28970830, 2017). "For example, in mice bearing recurrent B16 melanoma tumors, full tumor regression could only be achieved when anti-PD-L1 treatment was combined with Treg cell depletion or blockade of the inhibitory receptor LAG-3." (PMID 25875653, 2015). "Using anti-LAG3 or anti CTLA4 with anti-PD-1 is promising for MMRd CRC patients 41,42 and other cancers such as melanoma 43,44." (PMID 40027748, 2025). "LAG-3 is highly expressed in tumor-infiltrating CD8+ T cells in various cancers, but particularly high in samples from melanoma tumors." (PMID 40299510, 2025). "In melanoma-bearing mice on a Western diet, those receiving triple immune checkpoint blockade (ICB) targeting PD-1, CTLA-4, and LAG-3 showed diminished response compared to lean controls." (PMID 40565936, 2025). "An increased frequency in circulating CD38+ TIM3+ CD8+ T cells was observed following combined anti-LAG-3 and anti-PD1 therapy in patients with advanced melanoma." (PMID 40299510, 2025). "Morpheus-Melanoma clinically validated the MOA of tobemstomig, a bispecific that selectively engages PD-1/LAG-3 co-expressing TILs over LAG-3+ Treg cells." (PMID 40993242, 2025). "A PD-1/LAG-3 bispecific antibody, RO7247669/Tobemstomig is in early Phase I/II clinical trial for use in patients with melanoma, NSCLC, RCC and solid tumors (NCT05116202, NCT05419388, NCT05775289, NCT05805501, NCT04140500)." (PMID 40236693, 2025). "LAG-3 and TIM-3 are already the subject of clinical trials in the treatment of other cancers (e.g., melanoma, lung cancer, breast cancer), where their blockade leads to the activation of the immune response and increased therapy effectiveness." (PMID 40649775, 2025). "Thereafter, beneficial effects on CD8+ TIL responses have been reported in advanced melanoma and in patients with HNSCC treated with combined anti LAG-3 and PD1." (PMID 40299510, 2025). "The specimen is melanoma FFPE tissue stained with H&E and the biomarker LAG3 detected with the sCy7 chromogen." (PMID 39857048, 2025). "As mentioned, higher LAG-3 and CD8 expression in baseline tumors in patients with resected melanoma (RELATIVITY-098) enriched for RFS benefit in both the nivolumab plus relatlimab and nivolumab arms." (PMID 41109920, 2025). "For example, the LAG-3 inhibitor relatlimab combined with nivolumab is U.S. Food and Drug Administration (FDA)-approved for melanoma, while TIGIT and TIM-3 inhibitors are primarily being evaluated in combination with PD-1 inhibitors." (PMID 41181123, 2025). "Lymphocyte-activation gene 3 (LAG-3) inhibitors represent the third class of immune checkpoint inhibitors (ICIs) and have been approved by the FDA for the treatment of melanoma in combination with nivolumab since 2022." (PMID 40508177, 2025). "Obese melanoma mice tumors grow more rapidly and demonstrate leptin-induced T-cell exhaustion via overexpression of PD1, Lag3, and Tim3." (PMID 40565936, 2025).